NLRP3 (NLR family pyrin domain containing 3)
Diseases named in the same sentence as NLRP3 in open-access papers (continued):
Sharing a sentence is not in itself a finding about the gene and the disease.
prion disease (15 papers, 2012 to 2022). A transmissible disease that is caused by a protein that is able to induce abnormal folding of normal cellular proteins, leading to characteristic spongiform brain changes, which are associated with neuronal loss without an inflammatory response. "A second pathway implicated in in vitro models of prion disease is the Nod-Like Receptor Protein 3 (NLRP3) inflammasome, reported as the primary source of microglia-derived IL1β in prion infection." (PMID 36581683, 2022). "NLRP3-deficient mice showed similar incubation times compared to wild-type controls and displayed biochemical and neuropathological features characteristic of prion diseases." (PMID 25671600, 2015). "The role of the NLRP3 inflammasome in bona fide prion disease was assessed by intracerebral inoculation of Nlrp3−/− and Pycard−/− mice (C57BL/6) with RML prions." (PMID 33672129, 2021). "Therapies targeting the NLRP3 inflammasome shouldn’t be disregarded for prion diseases, although more in vivo studies, using a variety of infectious strains, are required to corroborate the in vitro data." (PMID 33776778, 2021). "Our previous work and other research groups revealed that PrP fibril, another misfolded protein in Prion disease, induced lysosomal destabilization and NLRP3 inflammasome activation." (PMID 30755589, 2019). "More studies on other forms of prion diseases are needed to verify the involvement of the NLRP3 inflammasome." (PMID 28337127, 2017). "This controversial state of affairs motivated us to investigate the contribution of NLRP3/ASC inflammasomes to brain levels of IL-1β in our experimental model of prion disease." (PMID 25671600, 2015). "Next, we studied temporal changes of NLRP3 inflammasome-related transcripts in the brain during prion disease development." (PMID 25671600, 2015). "Overall these data indicate that NLRP3 inflammasome-related transcripts are only marginally affected during prion disease." (PMID 25671600, 2015). "We found that these transcripts are either unchanged (Nlrp3 and Il1b) or only moderately upregulated (Pycard and, to a less extent, Casp1) in the latest stages of prion disease with respect to baseline levels." (PMID 25671600, 2015). "Here we set out to investigate the role of the NLRP3 inflammasome in prion disease in vivo." (PMID 25671600, 2015). "Here we have investigated the role of the NLRP3 inflammasome on prion disease in vivo." (PMID 25671600, 2015). "Based on these studies, it was postulated that pharmacological interference with the NLRP3 inflammasome/IL-1β signaling pathway could be beneficial against prion diseases." (PMID 25671600, 2015). "Whether the NLRP3 inflammasome contributes to the pathogenesis of Prion diseases remains debated." (PMID 28337127, 2017). "Our results exclude a significant role for NLRP3 and ASC in prion pathogenesis and invalidate their claimed potential as therapeutic target against prion diseases." (PMID 25671600, 2015). "Conversely, upon i.c. injection of 90 ng of non-infectious brain homogenate, Nlrp3-/- mice survived more than 450 days in the absence of clinical signs of prion disease." (PMID 25671600, 2015). "Based on these considerations, it is not excluded that an involvement of NLRP3 or ASC may become more apparent in specific forms of prion diseases different from those studied here." (PMID 25671600, 2015). "However, genetic ablation of NLRP3 or ASC in mice did not affect prion pathogenesis, suggesting that the NLRP3 inflammasome does not play a significant role in prion disease." (PMID 31015277, 2019). "However, genetic ablation of NLRP3 and ASC did not significantly delay the incubation period of RML-infected mice, suggesting that NLRP3 inflammasome and other ASC-dependent inflammasomes do not contribute to the pathology of prion diseases or that the effect is prion strain-dependent." (PMID 35979366, 2022).
sarcopenia (15 papers, 2019 to 2025). Progressive decline in muscle mass due to aging which results in decreased functional capacity of muscles. "To study the potential involvement of RIP3 in the activation of NLRP3 underlying sarcopenia in dependent patients, we examined the levels of RIP3 protein expression in skeletal muscle lysates by Western blot analysis." (PMID 38338718, 2024). "One inflammatory pathway underlying the development of sarcopenia is Nod-like receptor protein-3 (NLRP3) inflammasome, which is involved in the activation of the proinflammatory cytokines IL-1β and IL-18." (PMID 37373230, 2023). "Different signals can lead to the activation of the NLRP3 inflammasome and cause sarcopenia; for example, metabolic dysregulation due not only to obesity but also to insulin resistance leads to hyperglycemia and muscle atrophy via the WWP1/KLF15 pathway." (PMID 35954203, 2022). "NLRP3 activation has been proposed to contribute to sarcopenia, and NLRP3 knockout is protected against inflammation-induced and Duchene associated sarcopenia." (PMID 33806797, 2021). "Our results revealed the presence of morphologic sarcopenia hallmark, chronic lymphocytic inflammation and a type II fibers-selective NLRP3 expression associated to a significant decreased number of immunolabeled-fibers in aged animals." (PMID 33808510, 2021). "The NLRP3 inflammasome participates in age-related loss of muscle, and NLRP3 deletion mitigates the progression of sarcopenia in mice during aging." (PMID 31530994, 2019). "The NLRP3 inflammatory pathway was already reported to be involved in cardiac remodeling during pressure overload in an NLRP3 KO mouse model and resulted in reduced sarcopenia onset and progression, loss of muscle glycolytic potential, and mitochondrial dysfunction." (PMID 38338718, 2024). "Several pathways are involved in anthracycline cardiotoxicity and sarcopenia, including induction of lipid peroxidation, iron-related protein damages, high levels of pro-inflammatory cytokines, and intracellular NLRP-3 (inflammasome)." (PMID 38672567, 2024). "Based on the relevance of the inflammasome NLRP3 in elderly diseases and frailty, we investigated the implications of the activation of the NLRP3 inflammation pathway in human sarcopenia." (PMID 38338718, 2024). "In summary, we present evidence for the involvement of the NLRP3/ASC/NEK7/Caspase-1 inflammasome pathway with activation of pro-inflammatory SASP in the outcome of sarcopenia in the elderly." (PMID 38338718, 2024). "When NLRP3 is activated, impaired autophagy results in elevated IL-1β expression, which triggers the NF-κB signaling pathway, exacerbating the onset of sarcopenia." (PMID 39588187, 2024). "Our results revealed higher expression of gasdermin D in sarcopenic muscle from DP, further suggesting a connection between impaired autophagy and NLRP3-dependent inflammation in the development of severe sarcopenia." (PMID 38338718, 2024). "Altering mitochondrial function and biogenesis by increasing ROS production generates more inflammation, promoting increased activity of NLRP3 (pyrin domain of the Nod 3-like receptor family) that participates in sarcopenia." (PMID 36672642, 2023). "The perspective of the NLRP3 inflammasome reveals the necessity of finding new therapeutical approaches to attenuate inflammation and pyroptosis in sarcopenia." (PMID 35954203, 2022). "To better understand the role of NLRP3 in cardiac aging and age-related cardiac sarcopenia, we examined the left ventricle of different aged WT and NLRP3−/− mice." (PMID 34439517, 2021). "Nonetheless, there is evidence showing that the NLRP3 inflammasome appears to be involved in myopathies, muscle atrophy and sarcopenia." (PMID 33806797, 2021). "With these premises, we considered worthwhile to examine, for the first time, the expression of the NLRP3 inflammasome in skeletal muscle of aged cattle and its contribution to sarcopenia." (PMID 33808510, 2021).
sarcopenia (continued). "In our opinion, studies dedicated to clarifying the involvement of NLRP3 inflammasome in sarcopenia are required to better elucidate its potential role in mediating age-related inflammation." (PMID 33808510, 2021). "This field of research will also hopefully lead to new and specific therapies able to affect the deleterious consequences of the NLRP3 inflammasome-IL-1β/18 pathway activation in sarcopenia." (PMID 33808510, 2021). "Moreover, 24-month-old NLRP3-/- mice presented fewer signs of sarcopenia, as shown by improved muscle strength and endurance, higher glycolytic potential, and reduced muscle atrophy, than old control mice." (PMID 37373230, 2023). "Overall, the connection between SASP and NLRP3 provides a scenario where therapeutic targets against senescent cells (senolytics) and/or the NLRP3 inflammasome could prevent muscle degeneration and sarcopenia, killing two birds with one stone." (PMID 35954203, 2022). "We also suggest that the activation of the NLRP3 inflammasome may contribute to an increase in pro-inflammatory cytokines that have a pivotal role in inflammaging-related sarcopenia." (PMID 33808510, 2021). "So far, few studies have been dedicated to clarifying how the NLRP3 inflammasome may directly affect skeletal muscle during aging and a direct correlation between inflammasome and sarcopenia is still under investigation." (PMID 33808510, 2021). "However, the role of the NLRP3 inflammasome in human sarcopenia remains poorly understood." (PMID 38338718, 2024). "This hypothesis is supported by various studies that have demonstrated that IL1β, after being activated by NLRP3 inflammasome, plays a crucial role in the onset and disease progression of several myopathies, such as myositis, sarcopenia and Duchenne muscular dystrophy." (PMID 33802349, 2021). "By targeting CMA-mediated NLRP3 degradation, CTRP9 offers a promising therapeutic strategy for combating sarcopenia through coordinated modulation of differentiation pathways and muscle atrophy." (PMID 41057318, 2025). "The aim of this work was to evaluate, for the first time, the expression of NLRP3 inflammasome in bovine skeletal muscle in order to investigate the hypothesis that inflammasome activation may trigger and sustain a pro-inflammatory environment leading to sarcopenia." (PMID 33808510, 2021). "In human sarcopenic muscle from DP, we found a similar upregulation of these pathways, resembling sarcopenia to IBM and demonstrating the implications of the NLRP3 inflammasome in sarcopenic muscle from DP and the inflammatory nature of this debilitating condition." (PMID 38338718, 2024). "NLRP3 and Myd-88 are key orchestrators of chemotherapy-related cardiovascular diseases (CTRCD) and sarcopenia; cytotoxic properties are principally mediated by high levels of pro-inflammatory cytokines and chemokines, such as IL-1β, IL-6, IL-8, CXCL-2, TGF-β, IL-18 and others." (PMID 38672567, 2024).
systemic sclerosis (15 papers, 2017 to 2025). A chronic disorder, possibly autoimmune, marked by excessive production of collagen which results in hardening and thickening of body tissues. "Previous studies reported the role of NLRP3 inflammasome activation in a profibrotic phenotype in systemic sclerosis, but it was found to be impaired in IPF BALF macrophages." (PMID 37628972, 2023). "We showed that bleomycin requires the NLRP3 inflammasome to mediate fibrosis in an animal model of systemic sclerosis." (PMID 35625564, 2022). "Our laboratories have reported the role of NLRP3 in fibrotic disease systemic sclerosis/scleroderma." (PMID 35625564, 2022). "Our studies also implicate an autocrine loop between the IL-1 receptor, NLRP3 and fibrosis in patients with systemic sclerosis." (PMID 35625564, 2022). "The activation of the NLRP3 inflammasome contributes to multiple autoimmune diseases, such as ankylosing spondylitis (AS), systemic sclerosis (SSc), SLE, (SS), and RA." (PMID 35126351, 2021).
ankylosing spondylitis (14 papers, 2015 to 2025). An autoimmune chronic inflammatory disorder characterized by inflammation in the vertebral joints of the spine and sacroiliac joints. "However, in PBMCs from patients with ankylosing spondylitis, Sjogren’s syndrome and RA, NLRP3 was activated to initiate an inflammatory response." (PMID 39621557, 2025). "The efficacy was assessed using subjective tools [Bath Ankylosing Spondylitis Disease Activity Index (BASDAI) and Neck Disability Index (NDI) questionnaires) and objective measures (clinical markers, NLRP3 and IL-1β)." (PMID 40667507, 2025).
bronchopulmonary dysplasia (14 papers, 2019 to 2025). Bronchopulmonary dysplasia is a chronic respiratory disease that results from complications related to lung injury during the treatment of infant acute respiratory distress syndrome in low-birth-weight premature infants or from abnormal lung development in older infants. "Multiple early life events in the lung have been associated with NLRP3 activation, including viral and bacterial infections, Bronchopulmonary dysplasia and even septic events, which have been associated with increased susceptibility to later disease." (PMID 33923693, 2021). "VX-765 inhibited NLRP3/Caspase-1/GSDMD-mediated macrophage pyroptosis in the mice lung tissue of bronchopulmonary dysplasia (BPD)." (PMID 40486518, 2025). "In hyperoxia-induced lung injury, NLRP3 inflammasome activation elevates pyroptosis, contributing to bronchopulmonary dysplasia in premature infants." (PMID 41292520, 2025). "It has been suggested that caffeine inhibits the LPS‐induced macrophage MAPK/NF‐κB signaling pathway, suppresses the activation of the NLRP3 inflammasome, and improves bronchopulmonary dysplasia." (PMID 39312269, 2024). "Specific inflammasome subtypes, such as NLRP3 have been related to adverse neonatal outcomes, including bronchopulmonary dysplasia." (PMID 38892043, 2024). "In summary, our findings indicate that simvastatin could downregulate NLRP3 inflammasome activation and attenuate lung injury in hyperoxia-induced bronchopulmonary dysplasia via KLF2-mediated mechanism." (PMID 35509841, 2022). "Simvastatin could downregulate NLRP3-related pyroptosis and attenuate lung injury in hyperoxia-induced bronchopulmonary dysplasia via a KLF2-mediated mechanism." (PMID 36685920, 2022). "For example, acetate dampens the activation of NLRP3 inflammasomes in neonatal mice with bronchopulmonary dysplasia and protects lung injury; the L-tyrosine pathway, a metabolite produced by enteric microbes, impacts the airway epithelium at the distal end to reduce allergic airway reactions." (PMID 34768867, 2021). "Consequently, we hypothesized that simvastatin could protect against hyperoxia-induced bronchopulmonary dysplasia by suppressing NLRP3 activation and acting as an anti-inflammatory and antioxidant agent by upregulating KLF2 expression." (PMID 35509841, 2022). "In a mouse model of bronchopulmonary dysplasia, tert-butylhydroquinone (TBHQ), an Nrf2 activator, mitigates pyroptosis and enhances alveolar development by reducing NLRP3 inflammasome activation and oxidative stress." (PMID 41292520, 2025).
Infertility (14 papers, 2018 to 2025). "According to these findings, the NLRP3 inflammasome may be a novel therapeutic target for the management of infertility and may be linked to the age-dependent decline in female fertility." (PMID 39791737, 2025). "Furthermore, research has indicated the involvement of the NLRP3 inflammasome in age-related female fertility decline, suggesting its potential as a therapeutic target to address infertility issues associated with aging." (PMID 38068904, 2023). "This suggests that certain infertility cases may be caused by an activated NLRP3 inflammasome." (PMID 41369395, 2025). "In endometriosis, increased oxidative stress and NLRP3 inflammasome activation aggravate inflammatory lesions, resulting in tissue damage, adhesions, and infertility." (PMID 39791737, 2025). "Varicocele-associated infertility involves oxidative mtDNA activating the cGAS/STING pathway, which promotes NLR family pyrin domain-containing 3 inflammasome (NLRP3 inflammasome) activity and pyroptosis in Sertoli cells." (PMID 40331931, 2025). "This study is the first to determine seminal plasma and blood serum levels of NLRP3 protein in infertile men using the ELISA method in infertile men classified according to azoospermia and varicocele status." (PMID 37476898, 2023). "Statistically significant distinctions were observed when examining NLRP3 levels before treatment between the two infertility degree groups (p=0.013, Mann-Whitney U-test)." (PMID 38313171, 2023). "The authors found that the effects of NLRP3 and IL-1 inflammasomes are significant inflammation markers on mTESE success in azoospermic infertile men." (PMID 37476898, 2023). "We analyzed NLRP3 dynamics before and after treatment, considering different infertility degrees." (PMID 38313171, 2023). "It seems that the concomitant expression of NLRP3 and increased production of quantifying lipid peroxidation may be considered as a key target for treating infertility in such patients." (PMID 29034676, 2018). "This implies that in some instances of infertility, NLRP3 activation may play a role." (PMID 41369395, 2025). "This suggests that activation of the NLRP3 inflammasome could be part or player of some infertility situations, as stated in previous reviews, via an inflammatory cytokine storm and, it is likely that this could explain COVID-19-induced infertility as recently hypothesized." (PMID 35637440, 2022). "The mRNA level of the NLR family pyrin domain containing 3 (NLRP3) inflammasome was significantly higher in granulosa cells from patients with diminished ovarian reserve, showing infertility." (PMID 36979065, 2023). "Among the objective parameters we examined with the data we obtained from our study, we investigated the effect of serum and sperm NLRP3, IL-1β, TAS, TOS, and OSI markers determining intracellular oxidative stress in infertile men with azoospermia and varicocele." (PMID 37476898, 2023). "Inflammasome mechanisms, such as NLRP3 and IL1-β molecules, may provide additional benefit in evaluating the need and benefit of surgical or medical treatment in infertility with and without vascular pathology and with and without azoospermia." (PMID 37476898, 2023).